CTNNB1 (catenin beta 1)
Diseases named in the same sentence as CTNNB1 in open-access papers (continued):
Sharing a sentence is not in itself a finding about the gene and the disease.
tumor (continued). "Although tumours with mutations in CTNNB1 tend to have low-risk characteristics, they are related to worse outcomes with significantly increased rate of disease recurrence and lower overall survival." (PMID 35531470, 2022). "Several reports have shown both TCF7 and CTNNB1 is implicated in tumor formation and metastasis in several types of cancer." (PMID 36457029, 2022). "CTNNB1 gene alteration was the key mutation in LUAD that seems to promote proliferation of the tumor and then determine T stage." (PMID 35783357, 2022). "All the established primary culture PDT cells were examined to ensure that most of the cells were representative of the primary PDTs by comparing them with the original tumor tissues with the CTNNB1 mutation." (PMID 36539683, 2022). "Previous genomic analyses of desmoid tumor profiles have reported the presence of CTNNB1 or APC mutations, but only in a few oncogenic lesions." (PMID 36497457, 2022). "More than two different mutations in Ctnnb1 were found in 14 out of 20 tumor samples, strongly suggesting polyclonality in this model, in which multiple subclones containing different mutant alleles coexist in the tumor." (PMID 36313038, 2022). "Low allele frequencies (< 0.3) suggested that Dis3 and Rara mutations were subclonal, whereas a single copy of Ctnnb1 1004A>C (K335T substitution) with an allele frequency of 0.48 was likely to be clonal and thus possibly involved in tumor initiation." (PMID 35510955, 2022). "A multicenter Japanese study revealed that R1 resection, recurrent tumor, extremity location and CTNNB1 gene mutation status are adverse prognostic factors for postoperative local recurrence and preoperative drug treatment does not influence local recurrence." (PMID 35439723, 2022). "The mutation of CTNNB1 has been implicated in controlling tumor cell proliferation, differentiation, and progression, which due to its mutation, led to abnormal activation of the Wnt/β-catenin signaling pathway." (PMID 36582227, 2022). "Of note, HCC tumor cells, especially those with activating CTNNB1 mutations, highly rely on FAO for proliferation and survival 7, leading us to wonder how the resistant cells deal with the excess intracellular FAs when the fatty acid catabolism is inhibited." (PMID 36451864, 2022). "Excised specimens demonstrated nuclear ß-catenin expression more frequently in DF cases CTNNB1 mutated (34/38, 89.47%) than in CTNNB1 wild type tumours (13/22, 178 59.09%; p = 0.009)." (PMID 33914771, 2021). "Early detection of tumor-derived CTNNB1 mutations in urine cfDNA requires an assay, not only with high sensitivity, but with short amplicon size." (PMID 34441409, 2021). "The tumor harbored classical somatic changes of Wilms, namely canonical CTNNB1 and KRAS hotspot mutations and uniparental disomy of 11p." (PMID 34162837, 2021). "Allred score was significantly higher in tumours with CTNNB1 mutation (3.36 ± 2.26) compared with CTNNB1 wild-type tumours (1.74 ± 2.18) (p = 0.004)." (PMID 34420090, 2021). "An MYC transposon and transposase were co-injected to provide a second oncogenic driver necessary for tumor formation in conjunction with the Ctnnb1 mutation." (PMID 33837189, 2021). "In essence, the combined analysis of ctDNA and tumor tissue increased the detection rate of a CTNNB1 mutation in HCC patients." (PMID 33827453, 2021). "At inclusion, we detected the CTNNB1 p.T41A mutation in plasma in 9.5% of patients and the mutation rate was 13.5% when combining results from plasma and tumor tissue analysis." (PMID 33827453, 2021). "CTNNB1 mutations occur early during hepatic carcinogenesis and are trunk mutations, found ubiquitously in most cells within the tumor with minimal ITH at the genome level." (PMID 34771685, 2021).
tumor (continued). "Here, we explored the feasibility of detecting tumor-derived CTNNB1 mutations in cell-free DNA (cfDNA) extracted from the urine of HCC patients." (PMID 34441409, 2021). "At next-generation sequencing of 174 cancer-related genes, both neoplasms harbored a CTNNB1 somatic mutation which was different in each tumor." (PMID 33810291, 2021). "As the molecular profiling demonstrated that the tumor harbored the CTNNB1 S45F mutation which is associated with an aggressive phenotype, we performed adjuvant radiotherapy even after radical resection." (PMID 33429825, 2021). "In the univariate logistic regression model, tumours harbouring a CTNNB1 exon 3 mutation had a relative risk of relapse of 3.912 (p = 0.012)." (PMID 34420090, 2021). "This study aimed to evaluate the frequency of the CTNNB1 p.T41A mutation in ctDNA and tumor samples from HCC patients and to evaluate the concordance rates between plasma and tissue." (PMID 33827453, 2021). "CTNNB1 mutation was both sensitive to most tumours and specific; however, a small proportion of CTNNB1 wild‐type WNT cases alternatively harbour APC mutations." (PMID 33826763, 2021). "As expected, tumours harbouring CTNNB1 exon 3 mutation showed a higher LEF1 Allred score in accordance with proteomic data from CPTAC study." (PMID 34420090, 2021). "We examined the reasons why most of the patients with CTNNB1 mutations had recurrence despite complete tumor resection." (PMID 33140254, 2021). "FOXS1 overexpression decreased the transcription of β-catenin (encoded by the CTNNB1 gene) and two Wnt target genes in gastric cancer cell lines, which was associated with decreased tumor cell proliferation in mice." (PMID 34298659, 2021). "The tumor frequently harbors germline or somatic mutation of adenomatous polyposis coli (APC) or somatic mutation of CTNNB1, both of which lead to the accumulation of β-catenin in cytoplasm and nucleus of tumor cells, which can be detected by IHC." (PMID 35008368, 2021). "In conclusion, CTNNB1 mutation correlates with nuclear β-catenin expression in larger or excised DF tumours, and DF harbouring CTNNB1 mutations manifest variable clinical presentations." (PMID 33914771, 2021). "The tumor harbored an S45F mutation in CTNNB1, which has been correlated with a high recurrence rate." (PMID 33429825, 2021). "Such shifts are significant in posterior distributions of mutations, such as the S33P mutation in the CTNNB1 gene in the LIHC tumor type and the Q61R mutation in the HRAS gene in the THCA tumor type." (PMID 34424899, 2021). "Desmoid tumors frequently have mutations in APC or CTNNB1; however, mechanisms driving functional activation and tumor growth are not well understood." (PMID 34590610, 2021). "We showed that it is feasible to detect the CTNNB1 p.T41A mutation in both plasma and tumor samples using ddPCR." (PMID 33827453, 2021). "We examined the literature explaining the reason why most patients with CTNNB1 mutations encoding β-catenin, had recurrence after the complete tumor resection." (PMID 34298845, 2021). "Among them was patient U13, who had the highest mutant copy number before surgery, indicating that the CTNNB1 mutation detected in this patient’s preoperative urine was likely derived from the resected tumor." (PMID 34441409, 2021). "Male mice with an activating Ctnnb1 mutation and Hoxb9 overexpression develop tumours with increased proliferation." (PMID 33214683, 2021). "Combining analysis of ctDNA and tumor tissue increased the detection rate of CTNNB1 mutation in HCC patients." (PMID 33827453, 2021). "Adding results from plasma analyses increased the CTNNB1 mutation detection rate to 13.5% (5/37) in the subgroup of patients with tumor tissue available." (PMID 33827453, 2021).
tumor (continued). "MELF pattern of myoinvasion was less common in CTNNB1 mutant than wild-type tumours (5.3% vs 14.1%), and this was a focal finding in the only case with CTNNB1 mutation." (PMID 34420090, 2021). "Tumours with CTNNB1 exon 3 mutation were associated with reduced disease-free survival (p = 0.010), but no impact on overall survival was found (p = 0.807)." (PMID 34420090, 2021). "Relapses in tumours with CTNNB1 exon 3 mutation were locoregional in 4 patients and distant in 2 patients (metastases in mediastinal lymph nodes in one case, and multiple metastases in bone and liver in the other case)." (PMID 34420090, 2021). "Mutations in the CTNNB1 gene, which encodes the β-catenin protein, is highly prevalent in DF and is considered to contribute to tumour recurrence." (PMID 33914771, 2021). "As for specific mutations, five patients harbored four different CTNNB1 mutations, including p.T41I shared by all three tumor samples from P03, p.S45F shared in P07 and P10, p.S33C in P09, and p.S45F and p.K335T in LG-BilIN and GBC from P01, respectively." (PMID 34362903, 2021). "Further, we detected activating mutations in KRAS, ERBB2, RET, and CTNNB1, presumably conferring a new oncogenic driver in the respective tumor." (PMID 34201252, 2021). "When the Wnt signaling pathway is activated, CTNNB1 accumulation will occur in the nucleoplasm of tumor cells, leading to the loss of epithelial structural integrity and increased tumor invasion and metastasis." (PMID 34465343, 2021). "In the present study we aimed to prospectively monitor and evaluate the concordance between the CTNNB1 p.T41A mutation in ctDNA and tumor tissue in patients with HCC." (PMID 33827453, 2021). "In this study we applied ddPCR to detect the CTNNB1 p.T41A hotspot mutation in plasma and tumor tissue from HCC patients at inclusion and during 3 years of follow-up." (PMID 33827453, 2021). "Despite β-catenin accumulation being restricted to a minority of cells, CTNNB1 mutations have been identified in all of the epithelial tumour cells in a large cohort of ACPs by combining laser capture microdissection with deep sequencing." (PMID 34019103, 2021). "We found 15 cell cycle regulatory genes (E2F targets or G2M checkpoint Hallmark genes) upregulated in female Ctnnb1 tumours compared to Ctnnb1 male tumours, including Ccne1 and Cdk1." (PMID 33214683, 2021). "The Wnt signaling pathway is aberrantly activated in an SS18-SSX2 transgenic mouse model, and genetic loss of β-catenin (Ctnnb1) blocks tumor formation in this model." (PMID 32429395, 2020). "The clear connection between phenobarbital-dependent tumor promotion and β-catenin is underlined by studies showing the lack of tumor promotion in mice with conditional hepatocyte-specific knockout of Ctnnb1." (PMID 33097968, 2020). "In two of the three patients with somatic WT1 mutations, Wilms3 and Wilms11, no mutations in CTNNB1 were observed in the cell lines in comparison to the tumor DNA carrying a p.T41A and a p.S45F CTNNB1 mutation, respectively." (PMID 33379206, 2020). "In contrast, the constitutive, intracellular activation of Wnt signalling through APC or CTNNB1 mutation in LI tumours, renders upstream Wnt NRs functionally redundant and uncouples appropriate feedback loop equilibrium." (PMID 31563876, 2020). "This indicates that the tumor cell cultures first consist of a mix of cells and those cells harboring a CTNNB1 mutation were lost in culture." (PMID 33379206, 2020). "The tumour suppressive effect of E-cadherin, however, is overcome in the presence of homozygous CTNNB1 mutations indicating that threshold exceedance of mutated β-catenin levels also plays a role in colorectal neoplasia." (PMID 33115416, 2020). "One case with a germline APC variant harbored two concurrent somatic CTNNB1 variants at a different tumor site each." (PMID 31598872, 2020).
tumor (continued). "The aim was to segregate tumours into two clusters: LI tumours with identifiable mutations in APC or CTNNB1 and LD lesions with RSPO2/3 fusions or RNF43 alterations." (PMID 31563876, 2020). "It is possible, that the reduction of E-cadherin expression promotes tumour development by enhancing β-catenin nuclear activity, yet is caused by mechanisms different from CTNNB1 homozygous mutations in both, CRC cell line LS180 and CRC tissue." (PMID 33115416, 2020). "Gain of function mutations in the CTNNB1 gene encoding beta catenin allow the accumulation of beta catenin within the cell nucleus through WNT pathway und promote tumor progression in about 30% of cases in HCC." (PMID 32338295, 2020). "In their animal model study they show that heterozygous CTNNB1 mutations are drivers of tumourigenesis in the small intestine while in the large bowel homozygous mutations of CTNNB1 are necessary for tumour development." (PMID 33115416, 2020). "In the microdissected tumor from patient Wilms2, several different mutations in CTNNB1 were detected." (PMID 33379206, 2020). "Within both CTNNB1 mutation groups, there appeared to be a considerable heterogeneity in DNA methylation between tumor samples." (PMID 33194643, 2020). "Tumor promoting function of β-catenin has been repeatedly validated: oncogenic mutations in CTNNB1 frequently found in HCC patients; therapeutic effect in preclinical tumor models has been reported with drug targeting β-catenin." (PMID 31903133, 2020). "Recent study of HCC has shown that CTNNB1 gene mutations and overexpression of its encoded protein are closely related to occurrence, progression and prognosis of tumor." (PMID 32047745, 2020). "The current study results showed the overexpression of β-catenin among tumor samples as well as CTNNB1 mutated cases, being accompanied by overexpression of c-Myc." (PMID 32514293, 2020). "Two cell lines (Wilms3 and Wilms11) were established from tumors where the bulk tumor had a CTNNB1 mutation but the cell cultures were wild type." (PMID 33379206, 2020). "Several of the genes upregulated in CTNNB1-mutated tumours have previously been described as overexpressed in CTNNB1-mutated adrenal lesions, regardless of type of hormone production or differentiation level: AFF3, ISM1, NKD1, ENC1 and RALBP131,32." (PMID 31000732, 2019). "We defined three mutational subgroups: KCNJ5-mutated tumours, ATPase-mutated tumours and CTNNB1-mutated tumours." (PMID 31000732, 2019). "Three of these genes, apoptosis inhibitors BID, BIRC2 and BIRC3 were found in the differential expression analyses, being overexpressed in CTNNB1-mutated tumours." (PMID 31000732, 2019). "The main limitation of this study is the low number of included tumours, in particular with CTNNB1-mutation." (PMID 31000732, 2019). "On the contrary, mutations in CTNNB1 are known to cause cell proliferation and have been demonstrated to promote tumour growth in different contexts." (PMID 31000732, 2019). "Previous studies reported that activating mutations in CTNNB1 have oncogenic activity resulting in tumor development and somatic mutations are found in various tumor types." (PMID 31158229, 2019). "Of these genes, only CDK4 occurred in the differential expression analyses, being underexpressed in CTNNB1-mutated tumours." (PMID 31000732, 2019). "Based on transcriptome analyses, tumours carrying CTNNB1-mutations appear as distinct subset of APAs." (PMID 31000732, 2019).
tumor (continued). "One tumour with a CTNNB1-mutation was found to have substantially higher expression of both GNRHR and LHCGR than the other studied tumours." (PMID 31000732, 2019). "When CTNNB1-mutated tumours were excluded, 40 genes were found differentially expressed between tumours with KCNJ5 mutations and tumours with ATPase or CACNA1D mutations." (PMID 31000732, 2019). "Consistent with prior reports, our study found that the BRAFV600E mutation was the most common mutation in craniopharygiomas, and we also identified another tumor with a CTNNB1 mutation with a G34E substitution." (PMID 31712784, 2019). "Of note all significant differences in expression were between CTNNB1 mutated and CTNNB1 wildtype tumours." (PMID 31000732, 2019). "Somatic mutations in KCNJ5, ATP1A1, ATP2B3, CACNA1D and CTNNB1 have been described in ~60% of these tumours." (PMID 31000732, 2019). "Gene ontology enrichment analysis of transcripts differentially expressed in CTNNB1-mutated tumours shows overrepresentation of genes involved in ribosome and protein synthesis and protein trafficking pathways." (PMID 31000732, 2019). "The same observation on CTNNB1 were reported in a recent work that showed an association between CTNNB1 mutation in low grade EC patients and a higher risk of tumor recurrence." (PMID 29876005, 2018). "Both CTNNB1 wild-type tumours showed a copy neutral loss of heterozygosity within chromosome 5q (APC) and we identified APC frameshift deletions (E1309fs ΔAAAAG and Q1062fs ΔACAAA)." (PMID 30392813, 2018). "It has been found that the majority of ACP tumours harbour mutations in the CTNNB1 gene, encoding β-catenin." (PMID 28855316, 2018). "Although there are 20 shared mutations in genes between lung and other tissue site, CTNNB1 is the only known common gene that is mutated between these tumor tissues." (PMID 30301885, 2018). "The median overall survival rate for patients with tumours harbouring CTNNB1 mutations and deletions alone was significantly lower compared to the ones without (12.5 vs 77 months, log rank p = 0.0331)." (PMID 29872083, 2018). "β-catenin reduction in CTNNB1-mutated HCCs in a murine model led to complete tumor response, showing a clear benefit of therapeutic targeting of this molecule." (PMID 30073017, 2018). "It is proposed that CTNNB1 mutations stabilize β-catenin and increase the activity of the finely tuned Wnt signaling pathway, leading to tumor formation." (PMID 28102204, 2017). "The significantly mutated cancer-related genes that were identified in the tumor tissue compared to the adjacent normal control included CTNNB1 and VEGFR-2." (PMID 28915721, 2017). "Although prognostic factors other than CTNNB1 mutation have been reported such as age, size and location of the tumor, a biomarker reflecting a more mechanistic property of desmoid is necessary for better evaluation of prognosis." (PMID 28851389, 2017).